SLC43A2 (solute carrier family 43 member 2)
Description:
Uniporter that mediates the transport of the stereospecific L-phenylalanine, L-methionine and L-branched-chain amino acids, between the extracellular space and the cytoplasm and may control the transepithelial (re)absorption of neutral amino acid in kidney and small intestine. The transport activity is mediated through facilitated diffusion and is sodium ions-, chloride ions- and pH-independent Mediates the efflux of 3,3'-diiodo-L-thyronine (3,3'-T2) and 3-iodo-L-tyrosine (MIT).
Synonyms: LAT4; MGC34680
Tractability: Antibody: UniProt places it where antibodies can reach, with high confidence; its Gene Ontology location is reachable by antibodies, with high confidence; UniProt predicts a signal peptide or a membrane-spanning region. PROTAC: ubiquitination databases record sites on it; its protein half-life has been measured.
Gene: Protein-coding gene on chromosome 17 (1,569,268 to 1,630,103, reverse strand). Ensembl gene ENSG00000167703.
Subcellular location: Cell membrane; Basolateral cell membrane
Pathways (Reactome):
Transport of small molecules: Amino acid transport across the plasma membrane
Gene Ontology:
Molecular function: L-isoleucine transmembrane transporter activity; L-leucine transmembrane transporter activity; L-methionine transmembrane transporter activity; L-phenylalanine transmembrane transporter activity; protein binding; amino acid transmembrane transporter activity; L-amino acid transmembrane transporter activity; neutral L-amino acid transmembrane transporter activity; transmembrane transporter activity
Biological process: isoleucine transport; L-leucine transport; methionine transport; negative regulation of amino acid transport; negative regulation of L-leucine import across plasma membrane; phenylalanine transport; amino acid transport; neutral amino acid transport; amino acid transmembrane transport; L-alpha-amino acid transmembrane transport; transmembrane transport
Cellular component: plasma membrane; basolateral plasma membrane
Genetic constraint (gnomAD): Loss-of-function variants: 38 observed, 58.46 expected, observed/expected ratio (o/e) 0.65, 90% interval 0.5 to 0.85. The upper end of that interval is the gene's LOEUF score, 0.85, which puts it in group 3 of 6, group 1 being the genes least tolerant of losing a copy. Missense variants: 644 observed, 730.22 expected, observed/expected ratio (o/e) 0.88, 90% interval 0.83 to 0.94. Synonymous variants: 322 observed, 318.1 expected, observed/expected ratio (o/e) 1.01, 90% interval 0.92 to 1.11.
Homologues: Orthologues: chimpanzee SLC43A2 (99% identical), macaque SLC43A2 (98% identical), pig SLC43A2 (95% identical), dog SLC43A2 (95% identical), rat Slc43a2 (93% identical), guinea pig SLC43A2 (93% identical), mouse Slc43a2 (91% identical), rabbit SLC43A2 (84% identical), tropical clawed frog slc43a2 (83% identical), zebrafish slc43a2a (78% identical), zebrafish slc43a2b (76% identical). Paralogues in human: SLC43A1 (56% identical).
Diseases named in the same sentence as SLC43A2 in open-access papers:
SLC43A2 is named in the same sentence as 30 diseases in open-access papers, as found by Europe PMC text mining. Sharing a sentence is not in itself a finding about the gene and the disease. The quoted sentences say what the papers report.
malnutrition (3 papers, 2019 to 2023). Inadequate nutrition resulting from poor diet, malabsorption, or abnormal nutrient distribution. "The knockout of SLC43A2 mice led to growth restriction, postnatal malnutrition, and early death." (PMID 37048445, 2023).
melanoma (3 papers, 2023 to 2024). A malignant, usually aggressive tumor composed of atypical, neoplastic melanocytes. "As such, genetic ablation of SLC43A2 in mouse melanoma cells restored CD8+ T cell polyfunctionality and survival in vitro, and decreased tumor growth in vivo." (PMID 37842241, 2023). "It has been reported that SLC43A2 is mainly responsible for the Met uptake of melanoma cells." (PMID 38182561, 2024). "An analysis of The Cancer Genome Atlas (TCGA) database on RNA profiles obtained from melanoma, colon cancer and ovarian cancer revealed that PDCD1 is positively correlated with SLC43A2." (PMID 37147330, 2023). "While anti-PD-1 treatment or pharmacological inhibition of SLC43A2 alone did not elicit significant anti-tumor effects, combination treatment synergistically increased CD8+ T cell function and infiltration, and decreased growth of mouse melanoma and ovarian tumors." (PMID 37842241, 2023).
esophageal squamous cell carcinoma (2 papers, 2023 to 2025). Esophageal squamous cell carcinoma (ESCC) is a type of esophageal carcinoma (EC) that can affect any part of the esophagus, but is usually located in the upper or middle third. "NF-κB silencing results in a reduction in the expression of the methionine transporter SLC43A2, thereby downregulating methionine uptake in esophageal squamous cell carcinoma (ESCC)." (PMID 40430461, 2025).
heart failure (2 papers, 2011 to 2022). Inability of the heart to pump blood at an adequate rate to meet tissue metabolic requirements. "Analysis of the leucocyte transcriptome in 294 patients without overt heart failure revealed that levels of FECH, TMEM79, FBXW7, NGFB, ALK, UBN1, and SLC43A2 in peripheral blood were able to predict ALVD with 87% accuracy and 100% precision." (PMID 35722087, 2022). "UBN1, NGF and FECH genes displayed similar statistically significant regulation (up or down regulated) in hearts samples from heart failure patients but expression of the three remaining genes (TMEM79, FBXW7 and SLC43A2) could not be quantified, probably because of their low expression in heart." (PMID 21731613, 2011).
anxiety disorder (1 paper, 2021). A category of psychiatric disorders which are characterized by anxious feelings or fear often accompanied by physical symptoms associated with anxiety. "The stress environmental factors like early life adversity would trigger the DNA methylation change (Provençal and Binder, 2015), and epigenome-wide association study (EWAS) have reported many genes that showed epigenetic changes in anxiety disorders, including CFAP46, SLC43A2, and TNXB." (PMID 34650599, 2021).
breast carcinoma (1 paper, 2018). "A, gene expression (mRNA log2 values) of LAT common heavy chain (SLC3A2) and LAT transporters (LAT3/SLC43A1, LAT4/SLC43A2), was analysed in all breast cancer cell lines (n = 55) included in The Cancer Cell Line Encyclopedia (TCCLE)." (PMID 29940911, 2018).
colorectal cancer (1 paper, 2024). A primary or metastatic malignant neoplasm that affects the colon or rectum.
gastric cancer (1 paper, 2020). A primary or metastatic malignant neoplasm involving the stomach. "APBA2 encodes a tumor suppressor and was found to be hypermethylated in various cancers, and SLC43A2 was reported to be associated with gastric cancer; however, the prognostic value of these two genes is unclear." (PMID 33221755, 2020).
ovarian carcinoma (1 paper, 2023). A malignant neoplasm originating from the surface ovarian epithelium. "The Kaplan–Meier survival curve suggested that patients from TCGA ovarian cancer dataset with lower levels of SLC43A2 transcripts showed a good prognosis for overall survival." (PMID 37147330, 2023).
pancreatic cancer (1 paper, 2023). "In the current study, a total of 17 genes with prognostic values have been identified, of which 8 genes (SFXN5, LRRC8E, KCNJ10, UPB1, SLC43A2, SLC38A10, ACCS, and SLC38A5) were identified for the first time in pancreatic cancer." (PMID 37333498, 2023).
tumor (38 papers, 2013 to 2025). "Dysregulation of SLC43A2 has been implicated in tumor-mediated immune evasion, potentially by limiting methionine uptake in CD8 T cells." (PMID 40236422, 2025). "Since another methionine transporter encoded by SLC43A2 is also highly expressed in tumor cells, tumor-infiltrating effector T cells with low SLC43A2 expression levels do not compete with tumor cells for methionine." (PMID 37545500, 2023). "Moreover, PD-1 expression in tumor-infiltrating CD4 T cells from SLC43A2 deficient tumors was reported to be decreased." (PMID 38705513, 2024). "HCC cells highly express the methionine transporter SLC43A2, and its expression level positively correlates with tumor malignancy." (PMID 41293169, 2025). "The resulting positive feedback loop between SLC43A2 and NFκB signaling reduces ferroptosis and promotes tumor progression." (PMID 39218897, 2024). "Silencing SLC43A2 in a mouse melanoma cell line was shown to enable T cells to uptake more methionine in competition with tumor cells." (PMID 38705513, 2024). "Methionine/cystine restriction (MCR) and inhibition of SLC43A2, a methionine transporter, suppress tumor progression of esophageal squamous cell carcinoma by diminishing phosphorylation of IKKα/β and p65." (PMID 39218897, 2024). "Tumor cells compete with T cells for methionine via SLC43A2, resulting in metabolic and epigenetic impairment of T cell function and weakening tumor immunity." (PMID 39877420, 2024). "By inhibiting tumor SLC43A2 genetically and biochemically, T cells were able to restore H3K79me2, thereby boosting spontaneous and checkpoint-induced immunity." (PMID 37409118, 2023). "The solute carrier family (SLC) can transport methionine into cells, among which the high expression of SLC43A2 transporter in tumor cells will transport methionine fanatically resulting in reduced methionine available to T cells." (PMID 37532731, 2023). "The CRISPR plasmid targeting SLC43A2 restricted methionine metabolism in tumor cells and enhanced T cell immunity by relieving the methionine competition pressure of CD8+ T cells." (PMID 37532731, 2023). "In contrast, blocking tumor SLC43A2 restored H3K79me2 in T cells, thereby boosting their innate potency of tumor eradication." (PMID 37273004, 2023). "The level of H3K79me2 in tumor-infiltrated CD4 T cells was higher in SLC43A2 KO B16F10-bearing mice than in SLC43A2-intact B16F10-bearing mice." (PMID 37147330, 2023). "We further studied the effect of PMZH knockdown SLC43A2 on methionine content in vivo and anti-tumor immunity." (PMID 37532731, 2023). "SLC43A2 is a methionine transporter that tumor cells express at high levels, allowing them to monopolize methionine consumption." (PMID 37409118, 2023). "A positive feedback loop between SLC43A2 and NFκB signaling pathway regulated ferroptosis and tumor progression via controlling the GSH content and GPX4 expression." (PMID 37268653, 2023). "We detected the protein level of SLC43A2 in tumor tissues derived from the xenograft mouse model and in ESCC cells cultured in vitro." (PMID 37268653, 2023). "According to the ESCA cohort in TCGA database, the expression level of SLC43A2 was higher in tumor tissues than in normal tissues." (PMID 37268653, 2023). "As the transporter of methionine, SLC43A2 was reported as an oncogene to regulate methionine metabolism and tumor proliferation in many types of cancer." (PMID 37268653, 2023). "After supplementing methionine in tumor-bearing mice or inhibiting SLC43A2 expression in tumor cells, H3K79me2 and STAT5 expression were elevated and anti-tumor immune response of T cells was elevated." (PMID 35062950, 2022). "Inhibiting tumor SLC43A2 can normalize methionine metabolism in effector T cells, rescue their function and improve anti-tumor immunity in preclinical models." (PMID 36186480, 2022).
tumor (continued). "We explored the influence of SLC43A2 on tumor immune microenvironment (TIME), immune-related genes (IRGs) and the prognosis of liver hepatocellular carcinoma (LIHC) patients." (PMID 36186480, 2022). "Inhibition of tumor methionine uptake by knocking out SLC43A2, combined with anti-PD-L1 treatment, can enhance anti-tumor T cell responses and further inhibit tumor growth." (PMID 36569893, 2022). "SLC43A2 was found to impair T cell function, partly because the tumor cells highly expressed SLC43A2 and then outcompeted T cells for methionine." (PMID 36186480, 2022). "Tumor cells consume more methionine than T cells through high expression of the methionine transporter SLC43A2, thus disrupting methionine metabolism in CD8+ T cells." (PMID 36569893, 2022). "By over-expressing the methionine transporter SLC43A2, tumor cells avidly consume methionine and outcompete T cells for methionine, which disrupts the immunity." (PMID 34858835, 2021). "The recent study indicates that the SLC43A2 methionine transporter is a candidate for the target with high specificity in the tumor microenvironment." (PMID 34298902, 2021). "Tumour cells consumed methionine and “starving” T cells for methionine by expressing high levels of the methionine transporter SLC43A2." (PMID 33671588, 2021). "From a clinical point of view, tumour SLC43A2 correlated negatively with T-cell histone methylation." (PMID 33671588, 2021). "Genetic and biochemical inhibition of tumour SLC43A2 restored H3K79me2 in T cells and re-established tumour immunity." (PMID 33671588, 2021). "Studies have reported that SLC7A5, SLC1A5, SLC3A2, SLC43A1 and SLC43A2 are the major BCAA transporters in tumor cells." (PMID 33882453, 2021). "However, this transporter is also implicated in immune function, as a too high expression (as seen in tumor cells) reduces the availability of methionine for T cells, and downregulation of SLC43A2 can boost spontaneous and checkpoint-induced tumor immunity." (PMID 38350904, 2024). "Of all mentioned SLCs, only SLC7A5/6/7 and SLC43A2 revealed a negative association with overall survival, suggesting their high expression contributes to tumor progression." (PMID 38182561, 2024). "Therefore, supplementation of methionine and inhibition of tumour SLC43A2 can normalise methionine metabolism in effector T cells and restore their function, enhancing anti‐tumour immunity in preclinical models." (PMID 38935536, 2024). "The CRISPR/Cas9 system down-regulates the methionine transporter SLC43A2 and restricts the methionine uptake by tumor cells, thereby relieving the methionine competition pressure of T cells; simultaneously, the released nutrition metal ions activate the cGAS/STING pathway." (PMID 37532731, 2023). "We first evaluated the effects of PMZH on SLC43A2 expression in 4T1 tumor-bearing mice." (PMID 37532731, 2023). "SLC43A2 has been reported to participate in methionine transport in tumor cells." (PMID 37268653, 2023). "The results showed that PMZH could disrupt the protein expression of SLC43A2 in tumor cells efficiently via CRISPR/CAS9-mediated gene editing." (PMID 37532731, 2023). "Interestingly, PD-1 expression in tumor-infiltrating CD4 T cells from SLC43A2 KO tumor-bearing mice was reduced, whereas that in CD8 T cells did not change significantly." (PMID 37147330, 2023). "SLC43A2 transports methionine and it has been specifically shown that upregulation of this transporter in tumor cells depletes methionine in the tumor microenvironment leading to T-cell depletion and tumor evasion." (PMID 37803043, 2023). "However, to the best of our knowledge, the relationships between SLC43A2 and tumor immune microenvironment (TIME) as well as prognosis in LIHC have not been reported." (PMID 36186480, 2022). "Interestingly, the expression of the methionine transporter SLC43A2 in tumor cells leads to increased intracellular content of methionine." (PMID 36552330, 2022).
tumor (continued). "SLC43A2 played an important role in suppressing anti-tumor immunity, however, precise inhibition of SLC43A2 of tumor cells in vivo was difficult since it was widely expressed in various tissues such as the placenta, small intestine enterocytes, kidney epithelium, and peripheral blood leukocytes." (PMID 36186480, 2022). "A previous study, published in Nature, indicated that tumor SLC43A2 (solute carrier family 43 member 2) could modify T cell methionine metabolism and lead to T cell depletion." (PMID 36186480, 2022). "The same study found that the targeting and inhibition of the methionine transporter SLC43A2, which is highly expressed in tumor cells, resulted in the restoration of H3K79me2 histone modification in T cells, which led to higher checkpoint-induced tumor immunity." (PMID 34298902, 2021). "Moreover, tumor cells outcompete T cells for methionine via a major methionine transporter called SLC43A2." (PMID 34930302, 2021). "Intriguingly, it was found that SLC43A2 and SLC7A5 are expressed by tumor cells, but T cells mostly expressed SLC7A5." (PMID 38705513, 2024). "Since tumor cells rely on SLC43A2 for methionine uptake, here the authors design a nanoplatform for CRISPR/Cas9 mediated silencing of SLC43A2 and STING activation, restoring anti-tumor T cell immune responses." (PMID 37532731, 2023). "Disruption of SLC43A2 in tumor cells by PMZH would affect methionine metabolism in T cells and tumor cells." (PMID 37532731, 2023). "Further, the combined treatment of methionine and AICAR more suppressed tumor growth than methionine or AICAR treatment alone, suggesting additive effect of methionine and AICAR even for SLC43A2-KO tumors." (PMID 37147330, 2023). "Using readily available cancer databases, we investigated into the predictive potential of SLC43A2 on LIHC prognosis and its relationship with tumor-infiltrating immune cells." (PMID 36186480, 2022). "The combination treatment of SLC43A2 inhibitor and anti-PD-1 inhibited tumor growth and enhanced cytokine production by CD8+TILs in tumor-bearing mice." (PMID 34858835, 2021). "Interestingly, tumor-infiltrating effector CD8+T cells from humans and mice have lower levels of SLC43A2 expression, leading to reduced intracellular levels of methionine and SAM." (PMID 41293169, 2025). "Additionally, SLC43A2 and SLC35A2 are positively correlated according to TCGA database, hence the relationship between SLC35A2 and tumor immunity is worth exploring." (PMID 38639872, 2024). "Inhibition of SLC43A2 in tumor cells normalizes methionine metabolism in effector T cells and rescues their functionality, leading to improved spontaneous and ICB-induced anti-tumor immunity in murine tumor models." (PMID 34930302, 2021).